FTO (FTO alpha-ketoglutarate dependent dioxygenase)
Diseases named in the same sentence as FTO in open-access papers (continued):
Sharing a sentence is not in itself a finding about the gene and the disease.
endometrial cancer (continued). "E2-induced FTO, which is mediated through the activation of the PI3K/AKT and MAPK signaling pathways, has been shown to increase the proliferation and invasion of endometrial cancer cells." (PMID 40000966, 2025). "FTO functions by demethylating m6A modifications of HOXB13 mRNA, thereby promoting metastasis of endometrial cancer through activation of the WNT signaling pathway." (PMID 38200441, 2024). "FTO alpha-ketoglutarate dependent dioxygenase (FTO) can regulate the mRNA level of homeobox B13 (HOXB13) and promote the metastasis of endometrial cancer via modulating the WNT signaling pathway." (PMID 35156522, 2022). "The m6A demethylase FTO expression was found to be induced by estrogen in endometrial cancer via activation of PI3K-Akt and MAPK pathway where FTO was the downstream target of PI3K-Akt and MAPK." (PMID 33814008, 2021). "Thus, we hypothesized a stronger association of the FTO rs9939609 A allele and MC4R rs17782313 C allele and risk of the endometrioid type of endometrial carcinoma than with nonendometrioid types." (PMID 21347432, 2011).
cervical squamous cell carcinoma (26 papers, 2019 to 2025). A squamous cell carcinoma arising from the cervical epithelium. "On the contrary, FTO participates in the upregulation of repair gene resection repair cross complementation group 1 through β-catenin mRNA demethylation, equipping cervical squamous cell carcinoma with radiochemotherapy resistance." (PMID 39054967, 2024). "FTO also has been proved contribute to the chemo-radiotherapy resistance of cervical squamous cell carcinoma." (PMID 37402730, 2023). "The expression level of FTO is also elevated in cervical squamous cell carcinoma, which can enhance chemoradiotherapy resistance in vitro and in vivo by reducing m6A-regulated β-catenin expression." (PMID 35707365, 2022). "FTO promotes chemotherapy resistance by increasing the mRNA expression of β-catenin in cervical squamous cell carcinoma." (PMID 35923209, 2022). "High levels of FTO are characteristic in cervical squamous cell carcinomas, where they promote resistance to chemo/radiotherapy and increases DNA damage responses." (PMID 33741917, 2021). "The elevated level of FTO was also found in cervical squamous cell carcinoma (CSCC) and glioblastoma." (PMID 30922314, 2019). "Our analyses revealed lower abundance of METTL3 and FTO transcripts in cervical squamous cell carcinoma and endocervical adenocarcinoma (CESC), breast invasive carcinoma (BRCA), lung adenocarcinoma (LUAD), and colon adenocarcinoma (COAD) compared to their matched normal tissues." (PMID 38665783, 2024). "Likewise, FTO overexpression in cervical squamous cell carcinoma enhanced chemo-radiotherapy resistance via regulating b-catenin expression." (PMID 36497402, 2022). "On one hand, FTO overexpression inhibited cisplatin and irradiation-induced loss of cervical squamous cell carcinoma cell viability but FTO inhibitor MA2 increased the chemosensitivity of cervical squamous cell carcinoma cells." (PMID 34076564, 2021). "FTO is highly expressed in cervical squamous cell carcinoma (CSCC) tissues." (PMID 33072775, 2020). "In addition, FTO was found to enhance chemoradiotherapy resistance in cervical squamous cell carcinoma via β‐catenin." (PMID 32808488, 2020). "We also found nuclear FTO expression in the OED and OSCC, which corresponds with the previous studies on OSCC,9,10 hypopharyngeal, and cervical squamous cell carcinoma." (PMID 36582218, 2023). "The overexpressing of FTO in cervical squamous cell carcinoma (CSCC) was resistant to radiotherapy and chemotherapy by the FTO-mediated mRNA demethylation and ERCC1 activity." (PMID 36517820, 2022). "In cervical squamous cell carcinoma (CSCC), FTO can regulate the chemo-radiotherapy resistance by targeting β-catenin through mRNA demethylation." (PMID 33015074, 2020).
prostate carcinoma (26 papers, 2010 to 2025). A carcinoma that arises from epithelial cells of the prostate gland. "FTO downregulation has been associated with increased invasion and metastasis in various epithelial cancers, including breast and prostate cancers." (PMID 40722726, 2025). "This study aimed to evaluate the biological function and mechanism of fat mass and obesity-associated protein (FTO) in regulating m6A modification in prostate cancer development and epithelial–mesenchymal transition (EMT)." (PMID 38384328, 2024). "This study aimed at investigating the function and mechanism of demethyltransferase fat mass and obesity-associated protein (FTO) in prostate cancer(PCa)." (PMID 34787056, 2022). "Specifically, copy number loss of HNRNPC, METTL3, and FTO were significantly correlated with poor survival of prostate cancer, while patients with copy number gain of RBM15 and ALKBH5 had worse RFS." (PMID 32710725, 2020). "Individuals with more BMI increasing FTO alleles were less likely to be diagnosed with prostate cancer (OR per BMI increasing allele rs1558902-A 0.97; 95 % CI 0.94, 1.01, p = 0.10)." (PMID 26387087, 2015). "In addition, the present study results confirmed that FTO down-regulation was linked to poor prostate cancer prognosis and FTO knockout in AR-negative PC-3 cells promoted cell proliferation and migration via EMT." (PMID 38384328, 2024). "Association between FTO genotype and prostate cancer outcomes adjusted by age and study centre." (PMID 20976066, 2010). "The demethylase ALKBH5 with m6A binding proteins YTHDF1/2/3, concurrently, played a suppression role in the regulation of NSCLC tumor growth and metastasis, while FTO inhibits tumorigenesis in prostate cancer." (PMID 41157107, 2025). "Demethylases, also known as “erasers”, include FTO and ALKBH5, which function to remove the m6A methyl group from RNA and are also reported to be implicated in prostate cancer progression." (PMID 40830264, 2025). "Next, the interference of FTO expression in prostate cancer cells showed that the DDIT4 mRNA half-life was longer in cancer cells than in the wild-type cells, which indicated that m6A had a positive regulatory effect on mRNA stability." (PMID 38384328, 2024). "An EMT model of LNCaP and PC-3 cells was established with transforming growth factor-β treatment, and FTO knockout cell line was established in prostate cancer cells using the CRISPR/Cas9 gene editing technology." (PMID 38384328, 2024). "The current research suggested that FTO not only has a tumor suppressing function in prostate cancer but also a dual function as an m6A “eraser” in this disease." (PMID 38384328, 2024). "FTO, as a demethyltransferase, inhibited the m6A level in prostate cancer and induced EMT, thereby playing a dual role." (PMID 38384328, 2024). "An association was detected between m6A methylation and bone metastasis in prostate cancer, which showed that FTO knockout boosted DDIT4 expression and stimulated PC-3 cell invasion and EMT in vivo." (PMID 38384328, 2024). "In a previous study, the m6A “eraser” FTO was shown to regulate the m6A modification level of the EMT target gene DDIT4 in prostate cancer." (PMID 38384328, 2024). "Immunohistochemistry (IHC) results showed that METTL3 was up-regulated in prostate cancer, whereas FTO was down-regulated." (PMID 38384328, 2024). "Prostate cancer cells with FTO knockout were pretreated with CHX and MG-132 for 6 h and then treated with or without 10 ng/ml TGF-β for 48 h, followed by the detection of METTL3 and vimentin expression using western blot analysis." (PMID 38384328, 2024). "But there are also studies showing that knockdown of FTO reduced the migration and invasion ability of prostate cancer cells (Su, Wang & Li, 2021)." (PMID 37701836, 2023). "In contrast, certain studies have reported a tumor suppressor role of FTO in breast, colorectal, lung, bladder, and prostate cancer." (PMID 36497402, 2022).
prostate carcinoma (continued). "The results indicated that decreased FTO resulted in a decrease in the migration ability of prostate cancer cells." (PMID 34899855, 2021). "According to a new study in 2021, the m6A demethylase FTO inhibits the invasion and migration of prostate cancer cells by regulating and reducing the total m6A level." (PMID 34124065, 2021). "Knockdown of FTO significantly inhibited prostate cancer cells migration and invasion to further explore the biological function of FTO in prostate cancer, a series of in vitro experiments were performed." (PMID 34899855, 2021). "Premised on the expression of CBLL1, we also identified potential therapeutic agents for prostate cancer, and knockdown of FTO prominently inhibited prostate cells migration and invasion in vitro experiment." (PMID 34899855, 2021). "Transwell assay with Matrigel indicated that the invasion ability of prostate cancer cells was decreased due to the knockdown of FTO." (PMID 34899855, 2021). "It was also noted that prostate cancer patients with decreased FTO expression often had high tumor stage and high Gleason scores." (PMID 34899855, 2021). "So our study highlights that FTO is an oncogenic gene that promotes the progression of prostate cancer, and it is a potential novel therapeutic target for treatment of prostate cancer." (PMID 34899855, 2021). "We presented IGF2BP3, HNRNPA2B1 and METTL14 were significantly related to RFS of prostate cancer based on mRNA expression information, while in the CNV-based regression model, YTHDF2, FTO, and ALKBH5 were notably associated with prognosis of prostate cancer." (PMID 32710725, 2020). "In univariate Kaplan-Meir analyses, high expression of HNRNPA2B1 and low expression level of FTO had poorer RFS of prostate cancer." (PMID 32710725, 2020). "We found that the CNVs patterns of HNRNPC, METTL3, RBM15, ALKBH5 and FTO (one reader, two writers, and two erasers) were notably associated with RFS of prostate cancer." (PMID 32710725, 2020). "The result has shown that gene-level deletion of YTHDF3 (HR 0.42, 95% CI 0.19-0.95), FTO (HR 0.57 95% CI 0.35-0.9) and amplification of ALKBH5 (HR 2.48 95% CI 1.39-2.42) were risk factors of prostate cancer biochemical recurrence." (PMID 32710725, 2020). "Notably, downregulation of FTO worsens outcomes in bladder and prostate cancers, reflecting the complexity of tumor development and underscoring the need for personalized treatment based on m6A status." (PMID 40916616, 2025). "This suggests that FTO overexpression in lung and prostate cancers may impair CD70/CD80-mediated immune activation." (PMID 40565233, 2025). "Next, the cell proliferation capacity of FTO knockout prostate cancer cells was evaluated in vitro." (PMID 38384328, 2024). "In addition, the rate of RNA degradation in silent and knockout FTO prostate cancer cells and corresponding controls was measured." (PMID 38384328, 2024). "DDIT4, a target gene of EMT that is regulated by FTO, is involved in prostate cancer metastasis." (PMID 38384328, 2024). "Thus, this study revealed that the m6A demethylase FTO can play different roles in prostate cancer as a regulator of EMT and an inhibitor of m6A modification." (PMID 38384328, 2024). "Amplification of FTO was reported to significantly improve the prognosis of prostate cancer." (PMID 35814454, 2022). "In our study, we investigated the role of FTO in the proliferation of the prostate cancer cell." (PMID 34899855, 2021). "In addition, the magnitude of the effect of FTO on prostate cancer is expected, given its effects on BMI and the effects of BMI on prostate cancer." (PMID 22709667, 2012). "However, the possibility of pleiotrophy in the association between FTO genotype and prostate cancer risk cannot be completely ruled out." (PMID 20976066, 2010).
prostate carcinoma (continued). "An in-depth investigation was conducted into the functions of DDIT4 in the FTO-triggered EMT of prostate cancer cells, even though the promotion roles of FTO/TGF-β in EMT and prostate cancer development have been extensively established previously." (PMID 38384328, 2024). "The results showed that prostate cancer patients having higher METTL3 expression and lower FTO expression exhibited reduced disease-free survival (DFS)." (PMID 38384328, 2024). "The study results revealed down-regulated m6A methylation levels in prostate cancer cells undergoing EMT, with FTO as the regulator." (PMID 38384328, 2024). "In the matched clinical samples, the FTO level was down-regulated and METTL3 was up-regulated in most prostate cancer samples." (PMID 38384328, 2024). "However, the regulation mechanism of FTO in prostate cancer (PCa) remains unclear." (PMID 37529797, 2022). "Subsequently, we determined CBLL1, FTO, YTHDC1, HNRNPA2B1 as crucial m6A regulators of prostate cancer." (PMID 34899855, 2021). "Meanwhile, two important m6A “erasers”, FTO and ALKBH5 were significantly down-regulated in prostate cancer patients." (PMID 32710725, 2020). "Downregulation of FTO can promote the progression of PCa by targeting MCR4 in the way of m6A modification, while overexpression of MCR4 can promote the malignant progression of prostate cancer cells." (PMID 40830264, 2025). "The RNA and protein levels of METTL3 and FTO in RWPE-1, LNCaP, PC-3, 22RV1, and DU145 cells were assessed, and the results showed that METTL3 expression was up-regulated while FTO expression was down-regulated in prostate cancer cells." (PMID 38384328, 2024). "In addition, the expression levels of METTL3, FTO (Zhu, Li & Xu, 2021), YTHDF1-2, YTHDC2 were positively correlated with the Gleason score of prostate cancer." (PMID 37701836, 2023). "Indeed, different and sometimes contradictory results were also reported for kidney cancer concerning FTO and for METTL3 in prostate cancer." (PMID 35048498, 2022).
central obesity (24 papers, 2011 to 2025). "The MC4R rs12970134 association with BMI and the FTO rs8050136 association with central obesity appeared to be more pronounced with higher energy intake (β = 0.140 kg/m2, p = 0.049; OR = 1.77, p = 0.004, respectively)." (PMID 33668547, 2021). "A-allele of the FTO rs9939609 polymorphism was indicated to be associated with greater general and central obesity in adult population of Shiraz, Iran." (PMID 32398148, 2020). "The association of FTO gene with central obesity has been extensively investigated and well established." (PMID 25878631, 2015). "Another study from Japan also demonstrated significant association between FTO rs1558902 SNP and central obesity in adults." (PMID 23424664, 2013). "Participants with FTO risk allele (A) had significantly higher odds of being overweight/obese (OR: 0.19 (0.10–0.36), p < 0.001), central obesity (OR: 0.33 (0.15–0.71), p = 0.005), and visceral obesity (OR: 0.12 (0.06–0.23), p < 0.001) than individuals with the T allele only." (PMID 28607773, 2017). "Eleven types of variants in 4 genes (COL6A2, FTO, SPARC, and MTHFR) were found to be related to central obesity, and 8 of 48 subjects with MetS (16.7%) showed putative non-synonymous variants in these genes." (PMID 35999587, 2022). "The joint effect of four strongly associated SNPs (FTO rs9939609, MC4R rs17782313, GNPDA2 rs10938397, BDNF rs6265) on the risk of central obesity was further investigated." (PMID 23424664, 2013). "In conclusion, our study confirmed the significant association of four SNPs (FTO rs9939609, MC4R rs17782313, GNPDA2 rs10938397, BDNF rs6265) with risk of central obesity in the Chinese children." (PMID 23424664, 2013). "The results indicated that four SNPs (FTO rs9939609, MC4R rs17782313, GNPDA2 rs10938397, BDNF rs6265) and GRS calculated from these 4 SNPs significantly predicted the risk of central obesity." (PMID 23424664, 2013). "Our study replicates the statistically significant association of four SNPs (FTO rs9939609, MC4R rs17782313, GNPDA2 rs10938397, BDNF rs6265) with risk of central obesity in the Chinese children." (PMID 23424664, 2013). "Our study presents the new evidence that FTO rs9939609, MC4R rs17782313, GNPDA2 rs10938397 and BDNF rs6265 are statistically significantly associated with risk of central obesity in the Chinese children." (PMID 23424664, 2013). "Earlier, the author of the present study already reported the association of the FTO rs9939609 with BMI among the Liangmai tribe and central obesity in term of WHtR in Mizo tribe, in the present study, data of FTO gene were used for the purpose of gene–gene interaction analysis." (PMID 34414818, 2021). "Results of the present study on DASH score and WC/ WHR in individuals with minor allele of FTO variants are opposite of the reports of previous studies, which suggested that high adherence to DASH diet is associated with reduction in the risk of abdominal obesity." (PMID 37697388, 2023). "The most common genetic variant of the FTO gene (rs9939609 A/T) and a variant near the MC4R gene (rs17782313 C/T) were detected recently and both single nucleotide polymorphisms (SNPs) have been associated mainly with overall and, in some cases, abdominal obesity." (PMID 23849767, 2013). "A higher socioeconomic status aggravated the influence of SNPs (including FTO rs9939609, BNDF rs11030104, etc.)on BMI and WC, and aggravated the influence of SEC16B rs574367 on central obesity." (PMID 33668547, 2021). "A 12-year longitudinal study showed that FTO rs8050136 and GNPDA2 rs10938397 SNPs, rather than MC4R rs17782313, predicted persistent central obesity in the Chinese adults." (PMID 23424664, 2013).